EGFR (epidermal growth factor receptor)
Diseases named in the same sentence as EGFR in open-access papers (continued):
Sharing a sentence is not in itself a finding about the gene and the disease.
breast carcinoma (continued). "Direct targeting of EGFR is a promising therapeutic strategy for breast cancers with abnormalities in this pathway and may be beneficial in breast cancer patients who cannot tolerate surgery or traditional chemotherapy, or in advanced recalcitrant cases with poor prognoses." (PMID 22096483, 2011). "Thus, at the premalignant stage, EGFR inhibition may provide a window of opportunity for breast cancer prevention." (PMID 21396117, 2011). "We have previously reported that induction of epidermal growth factor receptor and ErbB2 in response to antihormonal agents may provide an early mechanism to allow breast cancer cells to evade the growth-inhibitory action of such therapies and ultimately drive resistant cell growth." (PMID 21396094, 2011). "Furthermore, we show that kin17 is necessary for EGF-stimulated cell growth, therefore, treatment targeting kin17 could be combined with neutral EGFR antibody therapy to treat breast cancer." (PMID 21980430, 2011). "This study investigated a series of matched primary and lymph node metastasis breast cancer tumors to demonstrate whether the expression of the CXCR4 and CCR7 chemokine receptors, along with expression of EGFR, predicts increased risk of metastasis and mortality." (PMID 20181250, 2010). "In addition, the expression of core basal markers such as EGFR, may lead to the application of targeted therapies, with EGFR inhibitors currently under investigation for use in basal-like breast cancers." (PMID 20520800, 2010). "In the continued search for additional biomarkers that may be predictive of response to anti-EGFR agents, we and others have extrapolated data from breast cancer, colorectal cancer, and NSCLC in order to address additional candidate genes/biomarkers to receptor tyrosine kinases in general." (PMID 21274259, 2010). "Even though Ras mutations are not prevalent in breast cancers, overexpression of its upstream tyrosine kinases, such as EGFR and Her2 neu, or constitutive activation of its downstream components leading to the activation of Ras signaling have been commonly observed in breast tumors." (PMID 20030805, 2009). "Jab1 is a target of EGFR signaling in ERα- cell lines and breast tumors and therefore may be a common central factor and potential therapeutic target for important cell signaling pathways in ERα- breast cancer." (PMID 18534028, 2008). "Currently, the prognostic significance of EGFR in breast cancer patients remains unclear." (PMID 18985033, 2008). "Epidermal growth factor receptor signalling through the PI3K–Akt pathway results in the activation of the transcription factor nuclear factor-κB (NF-κB) (constitutively active in ERα− breast cancers) and mammalian target of rapamycin (mTOR), an important regulator of protein synthesis." (PMID 18797454, 2008). "Several new drugs that target the EGFR in breast cancer are currently being evaluated and the observations presented here suggest that the effects of these drugs may become more apparent over the longer term, beyond the time over which a typical drug trial would extend." (PMID 17650314, 2007). "In the present study we have, for the first time, examined whether HRGs can similarly promote erbB3/PI3K/AKT signalling and effectively circumvent the inhibitory effects of the anti-EGFR agent gefitinib on the growth and invasion of an EGFR-positive Tam-R breast cancer cell line." (PMID 17686159, 2007). "Furthermore, blocking the pathway at the level of WNT/FZD/DVL, in contrast to targeting the β-catenin/TCF complex, would not only impact on canonical signaling but also provide a novel interface for interfering with autocrine EGFR activity, an important target in breast cancer." (PMID 17897439, 2007). "Furthermore, such a mechanism may be functional in the clinical setting as HRGβ1 is highly expressed in some EGFR-positive breast cancers, thus providing a possible de novo resistance mechanism to any utilized anti-EGFR therapy." (PMID 17686159, 2007).
breast carcinoma (continued). "Along the same line, the study of a large panel of breast carcinomas and oral squamous cell carcinomas established an inverse correlation between nuclear EGFR and patient survival, suggesting that nuclear EGFR accumulation may be indicative of poor clinical outcome." (PMID 17049074, 2006). "It suggest EGFR(Y1068) might serve as a promising molecular diagnostic marker to differentiate higher stage from lower degree of breast cancer and noncancerous mammary epithelial cells." (PMID 16288304, 2005). "Specifically, EGF-labeled liposomes have been used to direct eco-AgNPs to EGFR-overexpressing cells, while various nanotherapeutics have been conjugated with antibodies like Trastuzumab to target HER2-positive breast cancers." (PMID 41608666, 2026). "In a breast cancer xenograft model, Type-I UPTAB demonstrated approximately 80% tumor growth inhibition, reduced EGFR levels in tumors, and significantly extended survival." (PMID 42138807, 2026). "Compound I exhibited the highest EGFR and HER-2 inhibitory activity (IC50 = 0.09 μM for EGFR and IC50 = 0.42 μM for HER-2) in breast cancer (MCF-7) cancer cell lines relative to erlotinib." (PMID 41550831, 2026). "Compound II exhibited the highest antiproliferative efficacy against EGFR (IC50 = 0.122 μM) and HER-2 (IC50 = 0.078 μM) kinases, as well as MCF-7 breast cancer." (PMID 41550831, 2026). "The epidermal growth factor receptor (EGFR) is a well-established oncogenic driver in multiple epithelial cancers, yet its role in breast cancer remains elusive, with EGFR-targeted therapies showing limited clinical efficacy." (PMID 41932901, 2026). "The present investigation dealt with molecular modelling (docking) of the potent compounds showing their anticancer activities targeting cervical carcinoma HeLa cell line and breast cancer cell line MCF-7 for BCL-2 XL and EGFR." (PMID 41521222, 2026). "In further support, lapatinib, an EGFR/HER2 tyrosine kinase inhibitor, attenuated mitochondrial respiration in NF639 murine mammary tumor epithelial cells." (PMID 42089475, 2026). "To further evaluate translational potential, we tested EGFR and HER2 FolTAC-dual in patient-derived organoid (PDO) cultures established from two breast cancer patients (Patient 8 and Patient 10)." (PMID 41038820, 2025). "Breast cancer is classified based on molecular characteristics, including the expression of estrogen receptor (ER), progesterone receptor (PR), HER-2, EGFR, the cell proliferation marker Ki-67, and basal cytokeratins." (PMID 40806193, 2025). "We then analyzed the expression of epidermal growth factor receptors 1 and 2 (EGFR, HER2) in BLECs, hCMEC/D3 and two breast cancer cell lines: BT 474 (HER2-positive breast cancer cell line) and HC 1806 (triple-negative breast cancer cell line)." (PMID 41574208, 2025). "B-2 shows promise as an apoptosis inducer and EGFR inhibitor for future anti-NSCLC and anti-breast cancer research." (PMID 40806193, 2025). "EGFR, a tyrosine kinase receptor commonly overexpressed in tumors like HNSCC and breast cancer, plays a pivotal role in tumor progression." (PMID 40356890, 2025). "Lapatinib is a small-molecule tyrosine kinase inhibitor that targets EGFR and HER2, with unclear effects on pyruvate kinase type M2 (PKM2), and is used in the treatment of advanced HER-2-positive breast cancers." (PMID 41228310, 2025). "Low amounts of common antigens investigated for breast cancer, including HER2, MUC1, and EGFR, are also present in normal tissues, raising the possibility of unintentional CAR-T-cell activation and toxicities such “on-target, off-tumor” consequences." (PMID 39755633, 2025).
breast carcinoma (continued). "The coordinated actions of ERs with EGFR and IGF‐IR affect ECM composition (i.e., syndecan expression), Erk1/2‐dependent signaling, and crucial breast cancer cell properties, including migration and adhesion to fibronectin." (PMID 39285617, 2025). "The development of small-molecule EGFR inhibitors plays a crucial role in advancing treatments for NSCLC and breast cancer." (PMID 40806193, 2025). "Neratinib is another irreversible pan-HER inhibitor targeting EGFR, HER2, and HER4, currently approved for the treatment of HER2-positive breast cancer and currently under clinical development for other tumours, including CRC." (PMID 40940907, 2025). "Meanwhile, chalcone derivatives have been delved into for their potential EGFR-directed activities against NSCLC and/or breast cancer." (PMID 40006082, 2025). "Overall, bicyclic DDAs exhibit increased potencies and more pronounced biological responses in EGFR+ and HER2+ breast cancer cells." (PMID 40867591, 2025). "Study has shown that suppression of ANO1 expression significantly inhibits the phosphorylation of CAMKII, EGFR, Akt, and ERK1/2 in breast cancer, HNSCC, and ESCC cells." (PMID 40356890, 2025). "Quinoline/chalcone hybrids with 1,2,4-triazole moiety were examined for EGFR-directed anti-NSCLC and anti-breast cancer activity." (PMID 40006082, 2025). "In MCF-7 breast cancer cells induced by EGF, luteolin showed significant suppression of the expression of p-STAT3, p-EGFR, p-Akt, and p-Erk1/2 and inhibited cell proliferation." (PMID 40427522, 2025). "Overall, B-2 emerges as a promising small-molecule EGFR inhibitor with potential for further development against NSCLC and breast cancer." (PMID 40806193, 2025). "Several forms of breast cancer have been effectively treated using CAR-NK cells that target CD44v6, HER2, TF, B7-H6, EGFR, and PD-L1." (PMID 39755633, 2025). "The irreversible EGFR/ERBB2 inhibitor Neratinib, which is approved for the treatment of ERBB2‐positive breast cancers, emerged as a hit in our drug screening experiment for KRASi‐based combination therapies." (PMID 40956140, 2025). "In vivo experiments demonstrated GA1CAR T cells’ effectiveness in two breast cancer models targeting two different antigens (HER2 and EGFR)." (PMID 40614208, 2025). "Cytotoxic activity was evaluated against the MCF-7 breast cancer cell line using the MTT assay, whereas the in silico study was evaluated using molecular docking and molecular dynamics against the epidermal growth factor receptor (EGFR)." (PMID 41413149, 2025). "A study on cancer stem-like traits revealed that, in MDA-MB-231 breast cancer cells, subpopulations with high CD147 surface expression show enhanced membrane localization of CD44, EGFR, MCT4, ABCB1, and ABCG2, highlighting their coordinated interactions." (PMID 41479915, 2025). "Another study demonstrates that under hypoxic conditions, HIF-dependent upregulation of ADAM12 promotes breast cancer metastasis by enhancing HB-EGF shedding and activating EGFR–FAK signalling." (PMID 40427200, 2025). "Cd also induced epidermal growth factor receptor (EGFR), one of the important factors for IL-1 and IL-6, in breast cancer cells and human lung adenocarcinoma cell lines (A549)." (PMID 40771401, 2025). "We then evaluated the anticancer effects of these compounds against A549 NSCLC and MCF-7 breast cancer cells by MTT assay and, more mechanistically, the apoptotic effects in A549 and MCF-7 cells and the EGFR inhibitory potential of the most effective compound." (PMID 40006082, 2025). "Together, these findings establish EGFR and HER2 FolTAC-dual v1.0 as a potent and specific treatment for overcoming resistance in HER2+ breast cancer." (PMID 41038820, 2025). "In breast cancer, EGFR is overexpressed and can retro-translocate to the nucleus, potentially contributing to the underwhelming success of conventional EGFR tyrosine kinase inhibitor (TKI) and antibody-based therapies in breast cancer." (PMID 39521886, 2025).
breast carcinoma (continued). "We observed elevated expression in other key regions, such as EGFR and SCIN, which are well-known to be highly expressed in breast cancer resistance." (PMID 40946111, 2025). "More specifically, red and blue symbolize the positive regulation of migration and the regulation of the EGFR and IGF-IR signaling pathways; yellow represents ECM remodeling; purple stands for MMP activation; and green symbolizes breast cancer conditions." (PMID 40867236, 2025). "Dual-target inhibitors, e.g., lapatinib and neratinib, block both EGFR and HER2 and are used in breast cancer treatment." (PMID 39974747, 2025). "B-4 can be identified as a small-molecule EGFR inhibitor to be effective against NSCLC and breast cancer for future studies." (PMID 40006082, 2025). "In estrogen receptor-positive (ER+) breast cancers that HER2 and EGFR are overexpressed, downstream signaling components can be activated." (PMID 41035952, 2025). "OC demonstrated antiproliferative, apoptotic, anti-angiogenic, antimigratory, anti-invasive, and antimetastatic effects, mainly on breast cancer, by targeting ERα, HER2, EGFR, and c-MET." (PMID 40002421, 2025). "Curcumin reduces the level of epidermal growth factor receptor (EGFR), Akt, and matrix metalloproteinase (MMP2) while upregulating tissue inhibitors of metalloproteinase (TIMP-1) in breast cancer." (PMID 40563255, 2025). "Two RTK that have been connected to aberrant expression or hyperactivation in breast cancer are HER2 and EGFR." (PMID 39755633, 2025). "Breast cancer, a major global health challenge, is driven by aberrant receptor tyrosine kinase (RTK) signaling via epidermal growth factor receptor (EGFR) and vascular endothelial growth factor receptor (VEGFR)." (PMID 40640512, 2025). "Glucose consumption is upregulated in EGFRvIII mutant U87 glioblastoma cells, and in breast cancer cells treated with EGF or that overexpress EGFR." (PMID 39433211, 2025). "Chalcone derivatives have also been reported for their potential to target EGFR-driven NSCLC and/or breast cancer." (PMID 40806193, 2025). "In breast cancer, luteolin suppresses the expression of cancer-promoting proteins (p-Akt, p-STAT3, and p-EGFR), reduces progestin-dependent VGF secretion and cell growth viability, and increases Bax expression." (PMID 40487864, 2025). "In breast cancer, interactions between CD147, CD44, hyaluronan, EGFR, and MCT regulate tumor invasiveness and lactate metabolism." (PMID 41479915, 2025). "In MDA-MB-231 cells, miR-146 significantly downregulates epidermal growth factor receptor (EGFR) expression, inhibiting breast cancer cell invasion and migration in vitro and mitigating bone destruction." (PMID 41230330, 2025). "In summary, our findings emphasize the crucial role of EGFR and IGF-IR interactions in breast cancer progression and demonstrate the importance of using physiologically relevant 3D cell platforms in cancer research." (PMID 40867236, 2025). "The EGFR is a key transmembrane protein in the occurrence and development of NSCLC and breast cancer." (PMID 40006082, 2025). "In oncology, FM enhanced breast cancer stratification by increasing human epidermal growth factor receptor 2 (HER2) and epidermal growth factor receptor (EGFR) sensitivity." (PMID 41404488, 2025). "The hybridizing pyrazoline and thiazole scaffolds has proven effective in developing novel conjugates with targeted anticancer properties, including EGFR-specific activity against NSCLC and/or breast cancer." (PMID 40806193, 2025). "Compounds with the pharmacophore, such as NSC624205 and RBF3, displayed stronger effects toward EGFR+ (MDA-MB-468) and HER2+ (BT-474) breast cancers compared with the pancreatic cancer cell line (BxPC-3)." (PMID 40867591, 2025).
breast carcinoma (continued). "In HER2-expressing ovarian and breast cancer cell lines, responses to both lapatinib (anti-HER2 small molecule therapeutic) and erlotinib (anti-EGFR) were enhanced with exogenous OPCML." (PMID 40699804, 2025). "In breast cancer, IGFBP3 promotes the phosphorylation and nuclear translocation of EGFR and DNA-PKcs by facilitating their binding." (PMID 41199784, 2025). "Together, we establish a key regulatory circuit, RICTOR-AKT-ZFX-UGCG-Ganglioside-EGFR-AKT, and elucidate its contribution to breast cancer progression." (PMID 40934285, 2025). "EGFR and IGF1R, which drive signaling pathways involved in breast cancer development and progression, were also included due to their known crosstalk with E2-ER signaling pathways." (PMID 41228316, 2025). "In another study, simultaneous targeting of EGFR and CD73, an emerging checkpoint for cancer immunotherapy, was investigated as a new therapeutic approach for breast cancer." (PMID 39940134, 2025). "To determine if ambrosin inhibited EGFR phosphorylation, we stimulated serum-deprived bladder cancer and breast cancer cells with 10 nM EGF for 2 h to induce auto-phosphorylation of tyrosine 1068 (Y1068), a documented marker of EGFR activation." (PMID 40754248, 2025). "The unique and aberrant overexpression and/or activation profiles of RTKs in breast cancers, particularly HER2, hepatocyte growth factor receptor (MET), and EGFR, make them promising prognostic markers and therapeutic targets for disease management." (PMID 40560045, 2025). "Most studies on EGFR and FGF signaling in BCSCs rely not only on mammosphere assays and established breast cancer cell lines but also provide validation in patient-derived xenografts or clinical samples." (PMID 41373619, 2025). "RT-qPCR and Western blot analysis demonstrated that TSAC exerted an anti-breast cancer effect by suppressing the gene and protein levels of Src, PI3K, and EGFR." (PMID 40864816, 2025). "Taken together, our findings suggest that DNMT3A activates the EGFR-MEK-ERK signaling pathway by silencing ADAMTS8 transcription through methylation, thereby promoting breast cancer development." (PMID 40323963, 2025). "At the apex of oncogenic signaling cascades is EGFR and its inhibition by a monoclonal antibody, Cetuximab, stiffens A549, MDA-MB-231, and MCF-7 lung and breast cancer cells." (PMID 40498131, 2025). "In breast cancer, melittin suppressed the activation of human epidermal growth factor receptor 2 (HER2) and epidermal growth factor receptor (EGFR), two major drivers of tumor progression in HER2-enriched and triple-negative subtypes." (PMID 40871040, 2025). "For example, HDACi have been found to inhibit EGFR expression in non-small cell lung cancer (NSCLC), head and neck cancer, colorectal carcinoma, breast cancer, pancreatic adenocarcinoma and glioblastoma." (PMID 39864337, 2025). "Chalcones, which serve as precursors for pyrazolines, have also been reported to exhibit potential anticancer activity against EGFR-driven NSCLC and/or breast cancer." (PMID 40806193, 2025). "Our in vitro and in vivo studies demonstrate that the EGFR and HER2 FolTAC-dual degrader effectively suppresses tumor growth in Trastuzumab/Lapatinib-resistant HER2-positive breast cancer (HER2 + BC) models." (PMID 41038820, 2025). "In our recent study, we demonstrated the significant therapeutic contribution of both the pyrimidine core and chalcone moiety in combating EGFR-driven NSCLC and breast cancer." (PMID 40806193, 2025). "To date, pyrazoline–thiazole hybridization has been successfully used to design new conjugates with targeted anticancer activities, such as EGFR-directed activity against NSCLC and/or breast cancer." (PMID 40006082, 2025). "Among RTKs, the EGFR and the IGF-IR mediate signaling pathways that regulate the expression of target genes during breast cancer progression, thereby influencing cell proliferation, metabolic reprogramming, apoptotic evasion, EMT, invasion, and metastasis." (PMID 41228316, 2025).